BRCA2 (BRCA2 DNA repair associated)
Diseases named in the same sentence as BRCA2 in open-access papers (continued):
Sharing a sentence is not in itself a finding about the gene and the disease.
Klinefelter syndrome (11 papers, 2007 to 2025). A sex chromosome disorder caused by the presence of an extra X chromosome in the male karyotype. "Risk factors include heredity, particularly BRCA2 mutations (found in 26% of cases), reduced testosterone synthesis, and Klinefelter syndrome." (PMID 41321964, 2025). "The known risk factors associated with MBC are age, Klinefelter syndrome, BRCA2 mutation, high estrogen levels, gynecomastia, and cirrhosis of any cause." (PMID 31890398, 2019). "Risk factors associated with MBC include age, underlying genetics, including Klinefelter syndrome and BRCA2 mutations, radiation exposure, high estrogen levels, and liver cirrhosis as a result of excess alcohol consumption." (PMID 26044503, 2015). "Mutations in genes such as BRCA2 and PALB2 have been identified as contributors, with some cases associated with Klinefelter syndrome, emphasizing the diverse genetic landscape." (PMID 39512981, 2024).
liver cancer (11 papers, 2014 to 2026). An epithelial or non-epithelial malignant neoplasm that arises from the liver. "Recent data indicate that patients with liver cancer carrying a BRCA2 germline mutation may benefit from combination treatment involving olaparib." (PMID 39859548, 2025). "Our findings could offer an alternative management for patients with liver cancer harboring germline BRCA2 mutation." (PMID 32957395, 2020). "Here, we reported a HBV infected-patient with liver cancer carrying a BRCA2 germline mutation." (PMID 32957395, 2020). "We identified a BRCA2 germline mutation in a patient with liver cancer." (PMID 32957395, 2020). "However, in Patient 4 with a BRCA2 GPV, neither LOH nor a somatic pathogenic variant was identified, suggesting that the BRCA2 GPV may be unrelated to the liver cancer and instead represents an incidental finding." (PMID 40926019, 2026). "Moreover, HBV-infected patients with liver cancer might also carry a BRCA2 germline mutation, which further complicates treatment responses." (PMID 39859548, 2025). "The most common cancers in male relatives of BRCA2 carriers were lung (4.9%), esophageal (4.9%), and liver cancers (4.3%), followed by gastric (2.8%) and pancreatic (2.7%) cancers." (PMID 36861435, 2023). "In liver cancer, autoantibodies frequency to three TAAs were 25.0% (19/76), 5.3% (4/76) and 0% (0/76), 5.3% (4/76), 0% (0/76) and 0% (0/76) were shown to have autoantibody to PARP1 and BRCA1, PARP1 and BRCA2, or BRCA1 and BRCA2, respectively." (PMID 25865228, 2015).
acute myeloid leukemia (10 papers, 2014 to 2025). Acute myeloid leukemia (AML) is a group of neoplasms arising from precursor cells committed to the myeloid cell-line differentiation. "We modeled acquired cross-linker resistance with an FA-derived BRCA2-mutated acute myeloid leukemia (AML) platform." (PMID 28617445, 2017). "Flow cytometry-based single cell network profiling (SCNP) was used to measure drug-induced activation of DNA damage response (DDR) proteins in cell lines with defined HRR pathway mutations (including ATM-/-, ATM+/-, BRCA1+/-, BRCA2-/-) and in primary acute myeloid leukemia (AML) samples." (PMID 24965603, 2014). "Sorscher and coworkers reported a single BC case diagnosed at age 52 years and a personal history of acute myeloid leukemia (AML) who carried DH PSV in BRCA2/MLH1." (PMID 39102164, 2024). "Additionally, mutations in CHEK2 and BRCA2 have been linked to CLL and MDS, RAD51 in acute myeloid leukemia (AML) and MDS, MLH1 in MDS, and BRCA1 in AML." (PMID 34840720, 2021).
Anxiety (10 papers, 2016 to 2024). Intense feelings of nervousness, tension, or panic often arise in response to interpersonal stresses. "Overall, psychological and psychoeducational interventions for women with a BRCA1 or BRCA2 mutation are well-received by participants, and some have been shown to reduce distress, depression, and anxiety." (PMID 33804884, 2021). "Thus, prophylactic surgery of the reproductive organs not only decreases the mortality rate among patients with the BRCA1/BRCA2 mutations but also has a positive emotional effect, as it eliminates the patient’s constant anxiety about their own future, health, and, in particular, life." (PMID 31818005, 2019). "In view of the highly invasive interventions recommended in patients with pathogenic BRCA1 or BRCA2 variants, VOUS in these genes are particularly challenging and we hope our efforts will help alleviate the anxiety and confusion associated with at least some of these variants." (PMID 27884173, 2016).
brain cancer (10 papers, 2004 to 2024). A primary or metastatic malignant neoplasm affecting the brain. "Biallelic BRCA2 germline mutation carriers do develop childhood brain cancers as recently reported, although BRCA2 heterozygotes do not." (PMID 22275959, 2008). "No relatives of known BRCA1 or BRCA2 carriers were diagnosed with brain cancer." (PMID 20877337, 2010).
cholangiocarcinoma (10 papers, 2018 to 2025). A carcinoma that arises from the intrahepatic biliary tree (intrahepatic cholangiocarcinoma) or from the junction, or adjacent to the junction, of the right and left hepatic ducts (hilar cholangiocarcinoma). "Studies have shown that the presence of DDR mutations is significantly correlated with a higher TMB in cholangiocarcinoma, and patients with BRCA2 germline truncation mutations show an objective response." (PMID 37483430, 2023). "We describe a case of a woman with cholangiocarcinoma with transheterozygous BRCA1 and BRCA2 co-mutations who failed initial chemotherapy and was treated with targeted therapy for BRCA-positive patients." (PMID 38903278, 2024). "Although BRCA-associated cholangiocarcinomas are uncommon, even rarer is a mutation in both BRCA1 and BRCA2 genes." (PMID 38903278, 2024). "We present the first reported case of a patient diagnosed with cholangiocarcinoma found to have mutations in both BRCA1 and BRCA2 genes." (PMID 38903278, 2024). "We present a case of a patient with cholangiocarcinoma found to have mutations in both BRCA1 and BRCA2 genes." (PMID 38903278, 2024). "There are multiple documented genomic mutations associated with cholangiocarcinoma, and this includes the BRCA1 and BRCA2 genes." (PMID 38903278, 2024). "The significant difference between the sequencing methods also becomes evident in the example of a patient with cholangiocarcinoma, whose nonfocal loss of chromosome 13, which also affected BRCA2, was used as a co-rationale for PARP inhibition." (PMID 39794422, 2025). "Further study of this case, as well as future transheterozygous BRCA1 and BRCA2 cholangiocarcinomas, may provide further information on patients of this population and define a more targeted approach for individualized treatments." (PMID 38903278, 2024). "In addition to its own anti-tumor effects, Olaparib sensitizes cholangiocarcinoma cells to radiation if BRCA2 is positive." (PMID 37222808, 2023). "KKU-213, an HR-proficient cholangiocarcinoma cell line, was used to examine whether suppression of BRCA1 or BRCA2 expression sensitizes the cells to E7820." (PMID 38789724, 2024).
cutaneous melanoma (10 papers, 2014 to 2026). A primary melanoma arising from atypical melanocytes in the skin. "BRCA2 mutation carriers have been observed to have elevated risks for both uveal and cutaneous melanomas." (PMID 41142596, 2025). "In BRCA2 mutation carriers, both uveal melanoma and cutaneous melanoma were found at significantly increased frequency." (PMID 39795882, 2024). "In that study the risk was borderline significant for skin melanomas among BRCA2 carriers (6 observed, 2.3 expected); p = 0.05)." (PMID 38741145, 2024). "Mutations simultaneously affecting both BRCA1 and BRCA2 mainly occurred in head/neck squamous cell carcinoma (18.8%) and cutaneous melanoma (12.5%)." (PMID 33054725, 2020). "Cutaneous melanoma has been associated with mutations in the BRCA2 gene although there are only a few cases reported for uveal melanoma in BRCA2 mutation carriers." (PMID 24616882, 2014). "Cutaneous melanoma and BC share common mutations at susceptibility genes, like BRCA2 and CDKN2A." (PMID 32497148, 2020). "Carcinomas of the lung, bladder, stomach, and cutaneous melanoma were the frequent tumors demonstrating BRCAm in males, of which the majority were stage II or III diseases with a higher frequency of BRCA2 mutations." (PMID 33054725, 2020). "A pan-cancer analysis done on 33 cancers including cutaneous melanoma and uveal melanoma observed significantly higher HRDsum scores calculated based on LOH, LST, and TAI in patients with 22 different HRR mutations including BRCA1 and BRCA2." (PMID 41533995, 2026). "In cutaneous melanoma, mutations in BRCA1/2 were not statistically different between LOH-high and LOH-low (BRCA1: 1.30% v 1.12%, P = .705; BRCA2: 0.65% v 2.07%, P = .358)." (PMID 41533995, 2026).
endometriosis (10 papers, 2018 to 2025). The growth of functional endometrial tissue in anatomic sites outside the uterine body. "The BRCA1 variants in endometriosis (c.3232T > A) and PCOS (c.2566T > C) were identified within an OCCR of the gene and two BRCA2 variants in POI (c.7579delG, c.8524C > T) were identified to be within BCCR regions of the gene." (PMID 39359934, 2024). "Compared to BRCA carriers without endometriosis, those with endometriosis were more likely to carry a BRCA2 mutation, have post-secondary education, and experience earlier menarche." (PMID 41440203, 2025). "Participants with endometriosis were more likely to carry a BRCA2 mutation compared with those without endometriosis (34% vs. 28%, p = 0.012)." (PMID 41440203, 2025). "Endometrial expression of BRCA1 and Rad51 mRNA proved significantly lower in the endometriosis group (vs. controls), as did ovarian expression of BRCA1 and BRCA2 mRNA." (PMID 30622513, 2018). "Indeed, expression levels of BRCA1, Rad51, and ATM in endometrial tissue proved to be lower in the endometriosis group than in control subjects, as were expression levels of BRCA1 and BRCA2 in ovarian tissue." (PMID 30622513, 2018).
mesothelioma (10 papers, 2016 to 2025). A usually malignant and aggressive neoplasm of the mesothelium which is often associated with exposure to asbestos. "The amount of antisense-mediated BRCA2 mRNA knockdown was greater than 90% in both cell lines, similar to the amount of BRCA2 reduction in H2052 and 211H mesothelioma cells." (PMID 26959114, 2016). "In the same study, BRCA2 germline mutations were seen in 0.0152 proportion of mesothelioma patients as compared to the 0.003 estimate in non-cancer population (p=0.03)." (PMID 37020472, 2023). "Carriers of BRCA2 PVs (N = 1629) had a significantly increased risk for four core HBOC‐associated cancers (breast, ovarian, pancreatic, and prostate) and six additional types of cancer (lung, oral, small intestine, larynx, liver, and mesothelioma), hazard ratio (HR) > 2.37, all ps < 0.001." (PMID 40462315, 2025). "A recent Phase IIa clinical trial showed some activity of PARP inhibitors in mesothelioma patients with BAP1 and BRCA2 alterations (MiST1 trial)." (PMID 36138075, 2022).
neuroblastoma (10 papers, 2017 to 2025). Neuroblastoma (NB) is the most common solid, extracranial childhood tumor. "We found that high BRCA2 transcript was correlated with poor survival in neuroblastoma, likely due to its tight association with proliferation in these tumors." (PMID 39767807, 2024). "It therefore seems likely that the association between high BRCA2 and poor survival in neuroblastoma is most likely a result of BRCA2 marking cells with a high proliferative rate." (PMID 39767807, 2024). "Reasoning that USP44 promotes the activity of BRCA2, we hypothesized that high levels of BRCA2 may independently associate with outcomes in neuroblastoma." (PMID 39767807, 2024). "We found that HA-tagged USP44 co-precipitated both GFP-tagged and endogenous BRCA2 from SH-SY5Y neuroblastoma cells." (PMID 39767807, 2024). "We also found a very strong correlation between BRCA2 transcript level and a proliferation gene expression signature in neuroblastoma." (PMID 39767807, 2024). "Germline heterozygous mutations in BRCA1, BRCA2, and PALB2 were found in eight children with a spectrum of cancers including leukemia, CNS tumors, neuroblastoma, osteosarcoma, and rhabdomyosarcoma." (PMID 32962238, 2020). "BRCA2 is tightly correlated with a proliferation gene signature in neuroblastoma across the SEQC, Primary NRC, and TARGET datasets (Pearson R = 0.894, 0.870, and 0.876, respectively), perhaps explaining the association with these measures of aggressive disease." (PMID 39767807, 2024). "We next wondered whether the interaction between USP44 and BRCA2 may have implications for survival in patients with neuroblastoma." (PMID 39767807, 2024). "We also detected rare genetic germline variants in DNA repair genes (e.g., BARD1, BRCA2, CHEK2, and WRN) that might cooperate with somatically acquired variants in these patients with highly aggressive recurrent neuroblastoma." (PMID 33384420, 2020). "Particularly, germline mutations in BRCA2 and PALB2, that PALB2 binds to the N terminus of BRCA2 and has a key role in localization and stabilization of BRCA2, have been detected that they were associated with the development of neuroblastoma." (PMID 28055978, 2017).
soft tissue sarcoma (10 papers, 2016 to 2025). A malignant neoplasm arising from muscle tissue, adipose tissue, blood vessels, fibrous tissue, or other supportive tissues excluding the bones. "The patients with BRCA2 mutation (1x pancreas, 1x soft tissue sarcoma) received olaparib mono-therapy (plus pembrolizumab after 3 months in the case of soft tissue sarcoma) and continued treatment at time of data cut-off." (PMID 38136436, 2023). "BRCA2 mutations are infrequently reported in human soft tissue sarcomas." (PMID 35042909, 2022). "Cisplatin plus pemetrexed therapy was associated with sustained responses in patients with advanced and refractory soft tissue sarcoma (STS), and cisplatin-based chemotherapy resulted in a rapid major partial response in a patient with BRCA2-deficient STS." (PMID 37143137, 2023). "High PARP-1 expression alone and in combination with the expression of other DNA repair molecules (γH2AX, BRCA1, and BRCA2) is prognostic factor for shorter survival in soft tissue sarcoma patients." (PMID 33572586, 2021). "In support of our findings, studies have shown that RAD51 overexpression contributes to chemoresistance in human soft tissue sarcoma cells and rescues radiation sensitivity in BRCA2-defective cancer cells." (PMID 31640742, 2019). "The correlation between the clinicopathological variables and the expression of PARP1, γH2AX, BRCA1, and BRCA2 in soft tissue sarcomas." (PMID 27643881, 2016). "In this study, we evaluated the immunohistochemical expression of PARP1, γH2AX, BRCA1, and BRCA2 and their prognostic significance in 112 cases of soft tissue sarcoma (STS)." (PMID 27643881, 2016). "The expression status of PARP1, γH2AX, BRCA1, and BRCA2 according to the histological type of soft-tissue sarcoma." (PMID 27643881, 2016). "Kaplan-Meier survival analysis with Log-rank test according to the expressions of PARP1, γH2AX, BRCA1, and BRCA2 in various histological types of soft-tissue sarcomas." (PMID 27643881, 2016). "Univariate Cox proportional hazards regression analysis for survival in various subgroups of soft-tissue sarcomas according to the expression of BRCA1, BRCA2, PARP1, and γH2AX." (PMID 27643881, 2016).
bone marrow failure (9 papers, 2007 to 2024). "Rare hypomorphic biallelic BRCA2 mutations have also been associated with Fanconi anemia (FA), a syndrome characterized by developmental abnormalities and bone marrow failure." (PMID 39596525, 2024). "Although FA mice do not spontaneously develop bone marrow failure (except for mouse models of the FA-D1 group, harboring homozygous hypomorphic mutations in Fancd1/Brca2), treatment with MMC causes bone marrow failure in Fancc knockout mice." (PMID 18047734, 2007). "Since others have previously also documented successful HDR gene editing strategies to repair or compensate defects in FANCA, FANCC, FANCD1/BRCA2 and FANCI, the combined data support that gene editing can be a promising therapeutic strategy to prevent onset of bone marrow failure in FA patients." (PMID 30683899, 2019). "However, we identified a homozygous hypomorphic BRCA2 mutation in a patient with isolated POI without signs belonging to an FA phenotype at the time of the diagnosis, i.e., without bone marrow failure or developmental abnormality." (PMID 39596525, 2024).
kidney cancer (9 papers, 2012 to 2024). Primary or metastatic malignant neoplasm involving the kidney. "Our goal was to determine the prevalence of specific founder mutations genes BRCA1 (5328 insC, C61G and 4153 delA) and BRCA2 (C5972T) mutations in bladder and kidney cancer patients from Poland." (PMID 35395863, 2022). "The mutation in gene BRCA2 has been observed in two family cases with kidney cancer in first- and/or second-degree relatives." (PMID 35395863, 2022). "Fifty kidney cancer cases carried a BRCA2 mutation (7.3%) (OR = 1.3; 95% CI 0.93–1.80; p = 0.1)." (PMID 35395863, 2022). "Testing of interactions between BRCA2 and miR-19a/miR-19b in 15 cell lines derived from pancreatic, breast, colon, and kidney cancers showed that overexpression of these two miRNAs reduced BRCA2 expression by directly binding to its 3′-UTR." (PMID 32182776, 2020). "The mutations BRCA1 and BRCA2 seem not to play a role in bladder and kidney cancer development in Polish patients." (PMID 35395863, 2022). "In conclusion, this study reveals that mutations in BRCA1 gene (5328 insC, C61G, 4153 delA) and mutation (C5972T) of gene BRCA2 did not seem to play a major role in bladder or kidney cancer development." (PMID 35395863, 2022). "However, a relationship between kidney cancer and the BRCA2 mutation has not been reported thus far." (PMID 22353239, 2012). "To date, we have found no literature on the association of APC mutations with kidney cancer or of BRCA1, BRCA2 or APC mutations with liposarcoma of any kind." (PMID 39702187, 2024).
prostate adenocarcinoma (9 papers, 2015 to 2024). "Recently, the coordinated mono-allelic loss of BRCA2/RB1 on 13q was shown to evoke aggressive phenotypes in prostatic adenocarcinomas vulnerable to PARP inhibitor-based therapy." (PMID 35406559, 2022).